RNU6-1316P (RNA, U6 small nuclear 1316, pseudogene)
Gene: Small nuclear RNA gene on chromosome 14 (102,865,856 to 102,865,963, forward strand). Ensembl gene ENSG00000206969.
Homologues: Orthologues: dog U6 (92% identical), dog U6 (88% identical), mouse Gm25644 (88% identical), guinea pig U6 (87% identical). Paralogues in human: RNU6-1145P (94% identical), RNU6-20P (94% identical), RNU6-35P (94% identical), RNU6-38P (94% identical), RNU6-25P (94% identical), RNU6-434P (94% identical), RNU6-698P (94% identical), RNU6-1 (93% identical), RNU6-16P (93% identical), RNU6-2 (93% identical), RNU6-29P (93% identical), RNU6-393P (93% identical), and 1287 more.